SPCS3 (signal peptidase complex subunit 3)
Description:
Essential component of the signal peptidase complex (SPC) which catalyzes the cleavage of N-terminal signal sequences from nascent proteins as they are translocated into the lumen of the endoplasmic reticulum. Essential for the SPC catalytic activity, possibly by stabilizing and positioning the active center of the complex close to the lumenal surface (By similarity). (Microbial infection) Plays an important role in virion production of flaviviruses such as West Nile virus, Japanese enchephalitis virus, Dengue virus type 2 and Yellow Fever virus.
Synonyms: SPC22/23; SPC22; FLJ22649; SPC3; YLR066W; PRO3567; SPC23
Tractability: Antibody: UniProt predicts a signal peptide or a membrane-spanning region. PROTAC: ubiquitination databases record sites on it; its protein half-life has been measured.
Gene: Protein-coding gene on chromosome 4 (176,319,966 to 176,332,245, forward strand). Ensembl gene ENSG00000129128.
Subcellular location: Endoplasmic reticulum membrane
Pathways (Reactome):
Metabolism of proteins: SRP-dependent cotranslational protein targeting to membrane; Synthesis, secretion, and deacylation of Ghrelin; Synthesis, secretion, and inactivation of Glucagon-like Peptide-1 (GLP-1); Synthesis, secretion, and inactivation of Glucose-dependent Insulinotropic Polypeptide (GIP)
Disease: Maturation of DENV proteins; Maturation of hRSV A proteins
Cell-Cell communication: Regulation of CDH1 posttranslational processing and trafficking to plasma membrane
Gene Ontology:
Molecular function: protein binding
Biological process: protein processing; proteolysis; viral protein processing; protein targeting to ER
Cellular component: endoplasmic reticulum; endoplasmic reticulum membrane; signal peptidase complex; membrane
Genetic constraint (gnomAD): Loss-of-function variants: 0 observed, 4.8 expected, observed/expected ratio (o/e) 0, 90% interval 0 to 0.62. That is too few expected variants to judge how well the gene tolerates losing a copy. Missense variants: 71 observed, 101.84 expected, observed/expected ratio (o/e) 0.7, 90% interval 0.57 to 0.85. Synonymous variants: 58 observed, 47.69 expected, observed/expected ratio (o/e) 1.22, 90% interval 0.98 to 1.51.
Homologues: Orthologues: chimpanzee SPCS3 (100% identical), dog SPCS3 (100% identical), macaque SPCS3 (100% identical), mouse Spcs3 (100% identical), guinea pig SPCS3 (98% identical), rat Spcs3 (98% identical), pig SPCS3 (95% identical), tropical clawed frog spcs3 (86% identical), mouse Arxes1 (81% identical), mouse Arxes2 (81% identical), zebrafish spcs3 (75% identical), Drosophila melanogaster Spase22-23 (56% identical), and 1 more.
Diseases named in the same sentence as SPCS3 in open-access papers:
SPCS3 is named in the same sentence as 10 diseases in open-access papers, as found by Europe PMC text mining. Sharing a sentence is not in itself a finding about the gene and the disease. The quoted sentences say what the papers report.
Flavivirus Infections (2 papers, 2023 to 2024). Infections with viruses of the genus FLAVIVIRUS, family FLAVIVIRIDAE. "A previous genome-wide CRISPR KO screen uncovered both SPCS1 and SPCS3 as proviral factors for flavivirus infection, and depletion of SPCS1 led to inefficient polyprotein cleavage disrupting flavivirus production." (PMID 39261662, 2024). "A previous genome-wide CRISPR knockout screen uncovered both SPCS1 and SPCS3 as proviral factors for flavivirus infection, and depletion of SPCS1 led to inefficient polyprotein cleavage disrupting flavivirus production." (PMID 37398144, 2023).
cardiomyopathy (1 paper, 2023). A disease of the heart muscle or myocardium proper. "Spcs3 was reported to be differentially expressed in ischemic human and murine cardiomyopathy and in pressure-overloaded hearts." (PMID 36982963, 2023).
COVID-19 (1 paper, 2025). A disease caused by infection with severe acute respiratory syndrome coronavirus 2. "Within the dataset analyzed in this study, 4 out of 27 genes (14,8%) showed the 3′UTR shortening mechanism via APA (Δusage < −0.3), providing specific examples of potential escape from miRNA regulation in COVID-19 patients: CCNG2, PGS1, RTF1 and SPCS3." (PMID 41168347, 2025).
head and neck squamous cell carcinoma (1 paper, 2022). A squamous cell carcinoma that arises from any of the following anatomic sites: lip and oral cavity, nasal cavity, paranasal sinuses, pharynx, larynx, and salivary glands. "In the current study, we aimed to investigate the expression of the five microsomal signal peptidase complex (SPC) subunit genes (SEC11A, SEC11C, SPCS1, SPCS2, and SPCS3) in head and neck squamous cell carcinoma (HNSC) and to explore their prognostic value." (PMID 35653344, 2022).
viral infection (1 paper, 2013). "It seemed that knockdown of SPCS1 had a higher impact on the later stage of viral infection compared to either SPCS2 or SPCS3, which are possibly involved in the catalytic activity of the signal peptidase." (PMID 24009510, 2013).
infection (1 paper, 2024). The state of being infected such as from the introduction of a foreign agent such as serum, vaccine, antigenic substance or organism. "This suggests that SPCS3 and eIF3k may work together to inhibit CHIKV upon infection." (PMID 39261662, 2024).
tumor (1 paper, 2022). "Results showed that SEC11A, SPCS2 and SPCS3 were significantly upregulated in the tumor group than in the normal group." (PMID 35653344, 2022).
SPCS3 also shares sentences with these, for which no sentence is quoted: atherosclerosis (1 paper); retinal diseases (1); Stroke (1).